FAIM (Fas apoptotic inhibitory molecule)
Description:
Plays a role as an inducible effector molecule that mediates Fas resistance produced by surface Ig engagement in B cells.
Synonyms: FAIM1; FLJ10582
Tractability: Antibody: the Human Protein Atlas places it where antibodies can reach. PROTAC: ubiquitination databases record sites on it; its protein half-life has been measured.
Gene: Protein-coding gene on chromosome 3 (138,608,550 to 138,633,376, forward strand). Ensembl gene ENSG00000158234.
Subcellular location: Cytoplasm
Subcellular location (Human Protein Atlas): Cytosol; Plasma membrane
Gene Ontology:
Molecular function: protein binding
Biological process: negative regulation of extrinsic apoptotic signaling pathway via death domain receptors; negative regulation of apoptotic process; regulation of signal transduction
Cellular component: cytoplasm
Genetic constraint (gnomAD): Loss-of-function variants: 11 observed, 16.2 expected, observed/expected ratio (o/e) 0.68, 90% interval 0.43 to 1.12. The upper end of that interval is the gene's LOEUF score, 1.12, which puts it in group 4 of 6, group 1 being the genes least tolerant of losing a copy. Missense variants: 196 observed, 234.06 expected, observed/expected ratio (o/e) 0.84, 90% interval 0.75 to 0.94. Synonymous variants: 75 observed, 78.74 expected, observed/expected ratio (o/e) 0.95, 90% interval 0.79 to 1.15.
Homologues: Orthologues: macaque FAIM (97% identical), chimpanzee FAIM (94% identical), pig FAIM (94% identical), dog FAIM (93% identical), mouse Faim (91% identical), rat Faim (91% identical), rabbit FAIM (87% identical), tropical clawed frog faim (81% identical), rat Faiml (72% identical), mouse Faiml (68% identical), zebrafish faima (67% identical), guinea pig FAIM (67% identical), and 3 more.
Diseases named in the same sentence as FAIM in open-access papers:
FAIM is named in the same sentence as 17 diseases in open-access papers, as found by Europe PMC text mining. Sharing a sentence is not in itself a finding about the gene and the disease. The quoted sentences say what the papers report.
glioma (3 papers, 2022 to 2025). A benign or malignant brain and spinal cord tumor that arises from glial cells (astrocytes, oligodendrocytes, ependymal cells). "The influence of certain genes, such as DNA2, EGFR, FAIM, and HEATR3, on glioma risk, which is mediated through alterations in telomere length, enhances the elucidation of pathogenic mechanisms and introduces novel strategies for targeting telomere‐related pathways." (PMID 39722126, 2024). "Additionally, we identified five genes that not been implicated in glioma previously: CEP192 (18p11.21), D2HGDH (2q37.3) FAIM (3q22.3), HBEGF (5q13.3) and SLC8A1 (2p22.1)." (PMID 39565278, 2025).
lung adenocarcinoma (2 papers, 2022 to 2024). A carcinoma that arises from the lung and is characterized by the presence of malignant glandular epithelial cells. "For example, FAIM regulates autophagy induction in lung adenocarcinoma cells, thereby promoting cell proliferation." (PMID 39722126, 2024).
Alzheimer disease (1 paper, 2024). A progressive, neurodegenerative disease characterized by loss of function and death of nerve cells in several areas of the brain leading to loss of cognitive function such as memory and language. "It has been reported that miR-206 downregulates Fas apoptotic inhibitory molecule (FAIM), a protein implicated in blocking the formation of protein aggregates under stress conditions and whose isoforms are de-regulated in Alzheimer’s disease and dopaminergic neurons." (PMID 39290830, 2024).
amyotrophic lateral sclerosis (1 paper, 2020). Amyotrophic lateral sclerosis (ALS) is a neurodegenerative disease characterized by progressive muscular paralysis reflecting degeneration of motor neurons in the primary motor cortex, corticospinal tracts, brainstem and spinal cord. "Recent findings also show that FAIM could play a role in Amyotrophic Lateral Sclerosis inhibiting the aggregation of mutant SOD1, suggesting that FAIM participates in maintaining cell homeostasis." (PMID 33425889, 2020).
Parkinson disease (1 paper, 2020). A progressive degenerative disorder of the central nervous system characterized by loss of dopamine producing neurons in the substantia nigra and the presence of Lewy bodies in the substantia nigra and locus coeruleus. "Moreover, FAIM isoforms have been implicated in blocking the formation of protein aggregates under stress conditions or de-regulated in certain pathologies such as Alzheimer’s and Parkinson’s diseases." (PMID 33425889, 2020). "Disrupting the miRNA-mediated reduction of anti-apoptotic proteins such as FAIM, could represent a new neuroprotective strategy against neurodegenerative diseases such as Alzheimer’s or Parkinson’s." (PMID 33425889, 2020).
cancer (2 papers, 2022 to 2024). A tumor composed of atypical neoplastic, often pleomorphic cells that invade other tissues. "Research has shown that FAIM is implicated in the development of various cancers." (PMID 39722126, 2024).
infection (1 paper, 2017). The state of being infected such as from the introduction of a foreign agent such as serum, vaccine, antigenic substance or organism. "For example, the expression levels of some DEGs enriched in “negative regulation of apoptosis” functional pathway were up-regulated after infection, but other DEGs’ expression levels were down-regulated (including FAIM, CAT and KRT18)." (PMID 29073164, 2017).
kidney disease (1 paper, 2025). "There were 7 proteins that exclusively associated only with the kidney domain supporting their proximal role in kidney disease (e.g., A4GALT, PCK2, EFNA3, BTN3A2, IDI2, GATM, FAIM)." (PMID 41282674, 2025).
FAIM also shares sentences with these, for which no sentence is quoted: neurodegenerative disease (2 papers); Obesity (2); hypothyroidism (1); Insulin resistance (1); Intellectual disability (1); liver cancer (1); metabolic disorders (1); myeloma (1); Parkinson’s (1).